CEACAM1 (CEA cell adhesion molecule 1)
Diseases named in the same sentence as CEACAM1 in open-access papers (continued):
Sharing a sentence is not in itself a finding about the gene and the disease.
melanoma (continued). "There is an overwhelming expression of the CEACAM1-L isoform on melanoma cells, and elevated serum CEACAM1 levels were found to positively correlate with decreased patient's survival, failure to respond to immunotherapy, and decreased efficacy of autologous vaccination." (PMID 30406153, 2018). "High expression of CEACAM1 in the melanoma samples correlated with high cytoplasmic/nuclear Twist (φ = 0.20, p = 0.049) and also CEACAM1 staining in a certain area of an individual melanoma often correlated with cytoplasmic/nuclear TWIST staining intensity in the same area (serial sections)." (PMID 30089785, 2018). "CEACAM1 expression in melanoma of 113 patients could be investigated by staining for CEACAM1 using immunohistochemistry." (PMID 30089785, 2018). "This makes CEACAM1 inhibition an interesting option for combination therapy with immune checkpoint inhibitors (e.g. PD-1/PD-1L) as it would target additional factors/pathways that enable the melanoma cells to metastasize." (PMID 30089785, 2018). "Taking these findings together, we hypothesized that CEACAM1 might have direct functional relevance for melanoma metastasis involving melanoma cell-intrinsic mechanisms which are independent of T cell activation." (PMID 30089785, 2018). "However, CEACAM1 is widely expressed in melanoma, non-small cell lung cancers and lung adenocarcinomas, suggesting a degree of non-specificity as a biomarker." (PMID 29467960, 2018). "On the other hand, CEACAM1 expression modulates melanoma cell escape from immunologic attacks; when melanoma cells and tumor-infiltrating lymphocytes are coincubated in vitro, surviving melanoma cells increase CEACAM1 expression, which is dependent on constant presence of interferon gamma." (PMID 27642217, 2016). "CEACAM1 expression on melanoma cells protects them from an immune attack." (PMID 26885752, 2016). "Due to the high specificity and sensitivity of antibodies against CEACAM1 in melanoma metastases, it could enhance the standard immunohistochemical panel used in melanoma examination." (PMID 27642217, 2016). "Delineation of CEACAM1 regulation mechanisms in melanoma cells is therefore of clear importance." (PMID 26885752, 2016). "Notably, our data indicates that in melanoma cells Sp1 is involved in deactivation of the CEACAM1 promoter." (PMID 26885752, 2016). "Until now, several reports have focused on the role of soluble CEACAM1 in tumor patients and found elevated serum CEACAM1 level was relevant to tumor presence, progression and survival for patients with non-small cell lung, pancreatic cancers and malignant melanoma." (PMID 27074014, 2016). "Thus, CEACAM1 expressed on metastatic melanoma cells protects them from an immune attack, and CEACAM1 blockade renders the cells more susceptible to T cells." (PMID 26885752, 2016). "Finally, knockdown of SOX9 indeed renders melanoma cells resistant to T cell-mediated killing, in line with the increased CEACAM1 expression." (PMID 26885752, 2016). "CEACAM1 expression correlates with poor prognosis of melanoma patients." (PMID 27642217, 2016). "Also, our data agreed with Sivan who reported clinical significance of elevated serum CEACAM1 in malignant melanoma was superior to currently most used delayed-type hypersensitivity (DTH)." (PMID 27074014, 2016). "We have previously shown in two independent retrospective clinical studies that serum CEACAM1 is significantly higher in melanoma patients from different AJCC stages who show evidence of disease at the time of sampling, as compared to patients with no evident disease and healthy volunteers." (PMID 26688824, 2015). "As expected, the mean colony size was significantly reduced when cells where grown in a soft agar assay, indicating a crucial rule of CEACAM1-4L in anchorage-independent growth in malignant melanoma, which was further verified by the knock-down of endogenous CEACAM1 in UKRV-Mel-15a cells." (PMID 26539411, 2015).
melanoma (continued). "Moreover, following vaccination with modified autologous melanoma cells as postsurgical adjuvant therapy, the changes in postvaccination serum CEACAM1 correlate with overall survival and with the S100B melanoma marker." (PMID 26688824, 2015). "Here we focused on a novel emerging melanoma biomarker, serum CEACAM1." (PMID 26688824, 2015). "Thus, serum CEACAM1 is a potential novel prognostic biomarker for melanoma progression and predication of response to treatment." (PMID 26688824, 2015). "We conclude that serum CEACAM1 sensitively and accurately reflects tumor burden in xenografted mice and may therefore serve as a novel biomarker for the monitoring of melanoma tumor burden and progression." (PMID 26688824, 2015). "Interestingly, a melanoma-secreted form of CEACAM1 (sCEACAM1) has recently emerged as a potential tumor biomarker." (PMID 26688824, 2015). "In order to test whether serum CEACAM1 correlates with melanoma mass in vivo we used a xenograft model in which primary human melanoma cells are injected subcutaneously to SCID-NOD mice and serum CEACAM1 is measured by anti-human CEACAM1-based ELISA." (PMID 26688824, 2015). "Interestingly, the CEACAM1 expression levels in biopsies and concentrations of soluble CEACAM1 in sera of melanoma patients have been reported as a strong clinical predictor of poor prognosis and high risk of metastasis." (PMID 26539411, 2015). "In accordance with these findings, high levels of MMP-14 resulted in enhanced cleavage and proteolytic activity of MMP-2 in the human Ma-Mel-86a melanoma cell line expressing CEACAM1-4L, which in consequence, drives these cells to grow under anchorage-independent conditions." (PMID 26539411, 2015). "Moreover, we found that serum CEACAM1 inversely correlates with survival and can stratify melanoma patients with evidence of disease into two prognostic groups with different survival rates." (PMID 26688824, 2015). "In this context, evidence has amassed that expression of the multi-functional cell–cell adhesion protein CEACAM1 may be involved in the multistep process of metastatic spread in melanoma." (PMID 26539411, 2015). "By contrast, CEACAM-1 (CD66a) was only detected in 2 out of the 4 melanoma cell lines tested." (PMID 24489649, 2014). "A mouse antibody to CEACAM has no apparent effect on CEACAM1-expressing melanoma cells in vitro, but renders them susceptible to elimination by T cells in vitro and in an in vivo xenograft model." (PMID 24743024, 2014). "Importantly, patient-derived melanoma infiltrating lymphocytes and circulating T and NK cells from melanoma patients synthesize and express functional CEACAM1, which renders them susceptible to CEACAM1-mediated inhibition and may thus contribute to cancer progression." (PMID 22778766, 2012). "Therefore more malignant cells express CEACAM-1 in melanoma, while in other tumour entities such as breast or prostate cancer CEACAM-1 expression is down-regulated during malignant progression." (PMID 22162753, 2011). "CEACAM1 expression is frequently mis-regulated in cancer, with down-regulation reported in several tumors of epithelial origin and de novo expression of CEACAM1 in lung cancer and malignant melanoma." (PMID 21050451, 2010). "Therefore, UISO-Mel6 is the cell line of choice for analyses of CEACAM1 function in melanoma metastasis." (PMID 17262079, 2007). "Moreover, our studies may assist in the therapeutic monitoring of melanoma and lay the groundwork for the evaluation of CEACAM1 in other disorders." (PMID 38956268, 2024). "Notably, CEACAM1, CEACAM5, and CEACAM6 have been found to be implicated in immune related disease and cancer, and are now considered valid clinical biomarkers and promising therapeutic targets in melanoma, lung, colorectal, and pancreatic cancers." (PMID 36741860, 2023).
melanoma (continued). "Since CEACAM1 has been reported could inhibit cell proliferation, and cytotoxicity of T cells and NK cells in melanoma, a new anti-CEACAM1 antibody (MRG1) was used to bind to the N domain of CEACAM1, restoring the susceptibility of melanoma cells to attacked by T cells." (PMID 36497444, 2022). "Thus, an understanding of the pathways that give rise to tightly-controlled expression of CEACAM1 isoforms may offer new insights into the process of metastatic spread in melanoma." (PMID 30871206, 2019). "Subjected to alternative splicing, the CEACAM1 primary transcript generates 12 different human isoforms, 3 of which are secreted versions that play an important role in inhibition of intercellular adhesion, being a marker of melanoma, pancreatic, and urothelial bladder carcinoma (UCB) progression." (PMID 30406153, 2018). "Thus, novel insights into carcinoembryonic antigen cell adhesion molecule 1 (CEACAM1) may lead to promising strategies in melanoma treatment." (PMID 27642217, 2016). "In addition, it has recently been shown that the presence of soluble CEACAM1 in the serum reflects tumor burden in pancreatic adenocarcinoma patients and may have prognostic importance in melanoma patients." (PMID 26909604, 2016). "Thus, novel insights into CEACAM1 may lead to promising strategies in melanoma treatment, in monitoring melanoma patients, in assessing the response to immunotherapy, and in completing the standard immunohistochemical panel used in melanoma examination." (PMID 27642217, 2016). "Importantly, serum CEACAM1 could be detected in mice even at minimal tumor volume of 14 mm3 which may imply on its prognostic value as an early diagnosis of melanoma." (PMID 26688824, 2015). "We previously reported that the expression of CEACAM-1 and CD155 was increased on tumor cells in gastrointestinal metastases of malignant melanoma after anti-PD-1 therapy." (PMID 40801643, 2025). "Together, these studies support a role for CEACAM1 in the function of CD4+ Treg, TFH and Th2-related cells within the melanoma TME." (PMID 38956268, 2024). "There is a study suggesting that CEACAM1, particularly the CEACAM1-3S isoform, was able to induce enhanced expression of the NKG2D ligands MICA and ULBP2 on the surface of melanoma cells, which in turn contributed to NK cell-mediated cytolysis of tumor cells." (PMID 36712923, 2023). "The markers CEACAM1, FOSL1, IGFBP7, LXN and cytoplasmic/nuclear TWIST were used as predictors in a multivariate Cox model (adjusted for age) for the prognosis of the melanoma patients’ survival." (PMID 30089785, 2018). "High expression of CEACAM1 in the melanoma samples correlated with high FOSL1 (φ = 0.36, p < 0.001) and also CEACAM1 staining in a certain area of an individual melanoma often correlated with FOSL1 staining intensity in the same area (serial sections)." (PMID 30089785, 2018). "Currently, CEACAM1, CEACAM5, and CEACAM6 are considered as valid prognostic markers and promising therapeutic targets in melanoma, lung, colorectal, and pancreatic cancers." (PMID 29137373, 2017). "The authors compared the sensitivity of CEACAM1 and L1 markers to MelanA, S100, and HMB45 and describe results similar to other studies reporting an 87–93% sensitivity in primary melanomas and 60–95% in their corresponding metastatic lymph nodes." (PMID 27642217, 2016). "Serum CEACAM1, MICA and MICB were previously reported as poor prognostic markers in melanoma, but the relevance of pericardial involvement has never been evaluated." (PMID 26909604, 2016). "Simultaneously, in clinical studies of malignant melanoma, binding of the lectin HPA indicating aberrant glycosylation, and upregulation of the cell adhesion molecules CEACAM1 and L1, have been correlated with metastatic spread." (PMID 17262079, 2007). "Given that for this study we used exclusively primary NK‐cells from healthy donors, we cannot exclude the role of CEACAM1 in NKmK in melanoma patients despite the negative outcome of our experiments." (PMID 41078003, 2025).
melanoma (continued). "CEACAM1 is absent or at low levels on healthy circulating immune cells but is increased on immune cells in peripheral blood and tumors of melanoma patients." (PMID 38956268, 2024). "Melanocytes normally do not express CEACAM1, but it was found that in melanoma cells increased expression of CEACAM1 and decreased NKG2D ligands, lead to decreased susceptibility to NK cell-mediated cytolysis." (PMID 36741860, 2023). "CEACAM1 is downregulated prior to resistance development, suggesting that it may be a future target for the treatment of BRAF inhibitor-resistant melanoma." (PMID 33003483, 2020). "Melanoma patients benefit from the expression of CEACAM1-3S as a consequence of enhanced expression of the NKG2D ligands MICA, ULBP2 and DNAM-1 ligand CD155 on the surface of melanoma cells, thus presenting these cells as targets for NK cell mediated cytolysis." (PMID 30871206, 2019). "One of these adhesion molecules, named CEACAM1, is completely absent in normal melanocytes but highly expressed in most melanoma cells." (PMID 30871206, 2019). "In the melanoma samples, high expression of CEACAM1 did not correlate with low IGFBP7 expression and low IGFBP7 expression did not correlate with high LXN expression (φ = −0.01, p = 0.911 and φ = 0.03, p = 0.781, respectively)." (PMID 30089785, 2018). "The LXN low CEACAM1 kd MeWo tumors displayed reduced in vivo growth and metastasis in the spontaneous metastasis xenograft model and survival for patients with medium or high LXN melanoma on protein level (total of 105 samples) was significantly shortened." (PMID 30089785, 2018). "CEACAM1 homophilic interactions between TILs and melanoma cells appear to dampen in vivo TIL functions, limiting the efficacy of TIL adoptive cell transfer therapy in melanoma patients." (PMID 30406153, 2018). "CEACAM1 acts as a tumor suppressor gene in the PI3K/AKT pathway in certain epithelial tumors including clear cell RC, while de novo expression is a marker of cancer progression in other tumors including melanoma and thyroid carcinoma." (PMID 30233642, 2018). "The authors concluded that CEACAM1 expression in melanoma cells was an independent factor (regardless of the ulceration status, mitotic rate, and tumor thickness) for the risk of metastasis with a predictive value superior to that of tumor thickness." (PMID 27642217, 2016). "Our lab has previously shown that CEACAM1, a transmembrane glycoprotein abundantly expressed in most metastatic melanomas but not in normal melanocytes, is a key factor in the immune interaction between melanoma cells and activated lymphocytes." (PMID 26885752, 2016). "Compared with benign nevi, median expression of CEACAM1 was significantly increased in both thin and thick superficial spreading melanomas and was not significantly increased in dysplastic nevi." (PMID 27642217, 2016). "Expression of cell adhesion molecules CEACAM1 and L1 was analyzed and compared to expression of standard markers MelanA, S100, and HMB45 in 67 cases of primary melanomas, 40 cases of sentinel lymph nodes, 35 cases of distant metastases, and 12 cases of benign nevi." (PMID 27642217, 2016). "Regarding the specificity of immunohistochemical markers for melanoma cells, a relevant observation was described; CEACAM1 and L1 are highly specific for melanoma cells, while MelanA, S100, and HMB45 are not." (PMID 27642217, 2016). "Nevertheless, most studies in melanoma were focused on overall CEACAM1 without distinguishing the different isoforms." (PMID 26539411, 2015). "While it is expected that the pattern of nonhematological tissue-specific expression of CEACAM1 in melanoma patients would be similar to healthy donors, it has never been directly studied." (PMID 26688824, 2015). "For example, CEACAM1 is a negative prognosticator in melanoma, and we have found that only the long cytoplasmic domain splice variant is expressed in this cancer (unpublished results)." (PMID 18507857, 2008).
melanoma (continued). "Similar to clinical studies, HPA, CEACAM1 and L1 indicated metastatic spread in the xenograft melanoma model, but were not all simultaneously expressed in all cell lines." (PMID 17262079, 2007). "Due to its particular capacity to recognize CEACAM1 and CEACAM5 shared epitope, E8 recognizes a large panel of tumors (colon, breast and lung carcinomas and metastastic melanoma), and strongly binds tumors, such as lung carcinoma, that overexpress both the CEA proteins." (PMID 16504122, 2006). "However, our results did not indicate a significant increase in NKmK in CEACAM1 knockdown melanoma cells." (PMID 41078003, 2025). "Indeed, we found Ceacam1 gene expression to be upregulated in 1205Lu and WM793 after IFNγ treatment, a finding that suggested a possible existence of an alternative mechanism of melanoma resistance formation to NK‐cells." (PMID 41078003, 2025). "A detailed inventory of CEACAM1, PD1, and PD-L1 expression on immune cells in metastatic lesions to lymph node or soft tissues and peripheral blood samples from patients with treatment-naive and -resistant melanoma as well as peripheral blood samples from healthy controls was performed." (PMID 38956268, 2024). "As such, we show that CEACAM1 is largely absent or at low levels on healthy circulating immune cells but increased on immune cells in the peripheral blood and tumors of patients with melanoma." (PMID 38956268, 2024). "Interestingly, normal melanocytes are negative for CEACAM1, while melanomas often show high expression." (PMID 30871206, 2019). "Patients with melanoma also show a high percentage of CEACAM1 positive lymphocytes in the peripheral blood, which is not secreted and does not influence the total serum level of CEACAM1." (PMID 27642217, 2016). "CEACAM1 is a carcinoembryonic, antigen-related adhesion molecule 1 from the IG superfamily whose expression is absent from normal melanocytes, but often found in melanomas, particularly those that are metastatic." (PMID 24743024, 2014). "Interestingly, overexpression of CEACAM1-4L in originally CEACAM1 negative melanocytes and melanoma cell lines increased the migratory and invasive growth potentials, at least in vitro, supporting the role of CEACAM1-4L in melanoma progression and metastasis." (PMID 30871206, 2019). "Moreover, we demonstrate that serum CEACAM1 is elevated over time in progressive melanoma patients who fail to respond to immunotherapy as opposed to responders and stable disease patients, thus proving a correlation between sCEACAM1, response to treatment, and clinical deterioration." (PMID 26688824, 2015). "Moreover, we could identify CEACAM1-positive NK cells in lymph nodes infiltrated with CEACAM1-positive melanoma cells, but not with CEACAM1-negative melanoma cells." (PMID 22778766, 2012). "LOX is the cell line of choice for study of the functional role of HPA-binding carbohydrates in melanoma metastasis, as it shows intense HPA binding, does not express CEACAM1 and shows only low L1 expression." (PMID 17262079, 2007).